ALB (albumin)
Diseases named in the same sentence as ALB in open-access papers (continued):
Sharing a sentence is not in itself a finding about the gene and the disease.
ischemic stroke (117 papers, 2008 to 2026). A stroke disorder caused by obstruction of blood flow to the brain, due to thrombotic (local blood clot formation) or embolic (due to a blood clot or other material traveling from another site) event. "Previous studies had shown that albumin levels were related to the risk of early cardiovascular events and mortality in patients with ischemic stroke in the federated research network." (PMID 40353064, 2025). "Causal mediation analysis revealed that serum albumin levels partially mediated the association between dysphagia and delirium in critically ill patients with ischemic stroke (average causal mediated effect [ACME]: 0.02, 95% CI: 0.01 to 0.03; p < 0.001)." (PMID 38263028, 2024). "Albumin levels are associated with the risk of early cardiovascular events and death in patients with ischemic stroke." (PMID 38323429, 2024). "Albumin levels, measured within the first 24 hours after ischemic stroke, are associated with a higher risk of early cardiovascular events and death." (PMID 38323429, 2024). "High ratio of C-reactive protein to albumin in individuals with ischemic stroke is associated with an increased risk of HT and poor functional outcomes after thrombolysis." (PMID 36875705, 2023). "Previous literature suggested that serum albumin was associated with the prognosis of ischemic stroke." (PMID 36794538, 2023). "A cohort of studies with 24 years of follow-up discovered that low blood albumin levels were linked to a higher risk of total and ischemic stroke." (PMID 37682189, 2023). "Recent studies found that higher albumin-corrected calcium levels are related to a poorer short-term outcome and an increased risk of long-term mortality after ischaemic stroke." (PMID 36056314, 2022). "Similar trends were observed for first ischemic stroke; both low and high levels of serum albumin-corrected calcium were significantly associated with higher odds of first ischemic stroke." (PMID 35989922, 2022). "We also detected that ischemic stroke caused loss of the ChP blood–CSF barrier restriction of plasma albumin in the fenestrated ChP vasculature and increased CPECs’ uptake of albumin." (PMID 35413993, 2022). "We have shown that ischemic stroke caused robust extravasation of serum albumin into brain parenchyma, in parallel with detection of elevated ZT-1a levels in ischemic brain." (PMID 31911626, 2020). "Albumin treatment of ischemic stroke was associated with cardiopulmonary adverse events in previous studies and a low incidence of intracranial hemorrhage." (PMID 26325387, 2015). "The study objective was to determine the association between admission serum albumin levels and short-term outcome following acute ischaemic stroke in Nigerians." (PMID 23565300, 2013). "Low serum albumin levels are associated with an increased risk of ischemic stroke and ICH." (PMID 40584526, 2025). "In addition, our causal mediation analysis shows that serum albumin levels partially mediate the association between dysphagia and delirium in critically ill patients with ischemic stroke." (PMID 38263028, 2024). "Furthermore, studies have demonstrated a correlation between a decreased amount of serum albumin following an ischemic stroke and a heightened susceptibility to complications such as infection, cerebral edema, and hemorrhagic transformation." (PMID 38846203, 2024). "After adjusting for demographic variables such as sex, age, and race, we found that serum albumin levels partially mediated the association between dysphagia and delirium in critically ill patients with ischemic stroke (ACME: 0.02, 95% CI: 0.01 to 0.03; p < 0.001)." (PMID 38263028, 2024). "Additionally, higher serum albumin levels in ischemic stroke patients are associated with a lower likelihood of poor prognosis." (PMID 39835151, 2024). "Previous studies have shown that the decrease in albumin level or increase in globulin level might be associated with post-thrombolysis HT in ischemic stroke patients." (PMID 36158944, 2022).
ischemic stroke (continued). "In addition, studies have demonstrated the neuroprotective effect of ALB; that is, sufficient serum ALB is associated with reduced mortality and a better prognosis of ischemic stroke." (PMID 36457873, 2022). "However, numerous clinical studies on albumin and ischemic stroke overwhelmingly suggest that higher albumin levels are associated with better outcomes in ischemic stroke patients." (PMID 34572977, 2021). "High serum albumin levels during ischemic stroke (IS) decrease the risk of a poor outcome." (PMID 26757706, 2016). "In a recent publication investigating the association of serum albumin concentrations and ischemic strokes, the authors found a significant association between low serum albumin levels and, in particular cardioembolic and cryptogenic infarctions suggesting PFO might be a factor." (PMID 25678897, 2015). "The real‐time dual‐channel imaging of BBB disruption and cerebral vessels was also realized through the effective combination with the albumin‐escaping IR‐800Ac probe, offering insights into the mechanisms of ischemic stroke." (PMID 39999308, 2025). "In rodent models of ischemic stroke, albumin therapy has been shown to exhibit significant neuroprotective effects, including reduced brain infarct volume, improved neurological scores, and normalization of diffusion-weighted imaging changes." (PMID 40353064, 2025). "Nonetheless, the therapeutic use of albumin infusion during the acute phase of ischemic stroke remains controversial." (PMID 41180526, 2025). "Accumulating evidence indicates that serum albumin levels significantly influence clinical outcomes in individuals with ischemic stroke." (PMID 41180526, 2025). "More importantly, in situ NIR‐II FPs generated by the reliable interaction between the chromophore and albumin not only provided a direct visualization of albumin leakage but also enabled high‐precision imaging of BBB disruption during ischemic stroke." (PMID 39999308, 2025). "The albumin-to-globulin ratio (AGR) is a biomarker reflecting both nutritional status and inflammation, which has recently been implicated in the development of ischemic stroke." (PMID 41180526, 2025). "The lack of benefit from early combination therapy, however, warrants further investigation by considering albumin’s potential effects in the context of ischemic stroke." (PMID 41468394, 2025). "Albumin therapy has been shown to offer neuroprotective effects in ischemic stroke by modulating immune and inflammatory responses." (PMID 40332503, 2025). "Albumin protects against disorders of the central nervous system, such as ischemic stroke, Alzheimer’s disease, and SAH." (PMID 39539653, 2024). "Each of these trials focused on studying patients who had experienced an ischemic stroke to establish a connection between blood albumin levels and short-term functional results." (PMID 38846203, 2024). "In the subgroup analysis stratified by age, preoperative β‐blockers, and fibrinogen‐to‐albumin ratio (FAR), the association between CHD and perioperative ischemic stroke was stable (p for interaction >0.05)." (PMID 39185787, 2024). "The non-ischemic stroke group had significantly higher C-reactive protein (76.76 ± 88.32 vs. 29.74 ± 51.49; p < 0.001) and significantly lower albumin (3.56 ± 0.72 vs. 3.80 ± 0.73; p = 0.035) levels than did the ischemic stroke group." (PMID 39734631, 2024). "Recently, albumin has been found to exert a neuroprotective effect on the occurrence and development of ischemic stroke." (PMID 39403266, 2024). "In addition, the study aimed to investigate the potential mediating role of serum albumin levels in the association between dysphagia and delirium in these patients, with the aim of providing evidence to inform the clinical prevention, management and care of dysphagia after ischemic stroke." (PMID 38263028, 2024). "Previous research has established that serum albumin is a dependable marker for predicting long-term outcomes after an ischemic stroke." (PMID 38846203, 2024).
ischemic stroke (continued). "Recent research indicates a likely correlation between serum albumin levels and the prognosis of ischemic stroke." (PMID 38846203, 2024). "Glycated albumin (GA) is an indicator of glycemic variability over the past 2–4 weeks and has suitable characteristics for predicting the prognosis of ischemic stroke during the acute phase." (PMID 39127620, 2024). "Previous studies had shown that serum albumin was an independent prognostic factor for ischemic stroke." (PMID 39807247, 2024). "Serum albumin, as a multifunctional protein, plays neuroprotective roles in ischemic stroke by reducing erythrocyte aggregation and exhibiting an antioxidant effect." (PMID 36918775, 2023). "In the case of ischemic stroke, a meta-analysis of four studies was conducted to evaluate the neurofunctional outcomes of patients treated with albumin therapy." (PMID 37762860, 2023). "Serum albumin, a unique multifunctional protein, is reported to exert significantly neuroprotective effects against ischemic stroke via reducing the hematocrit level and inhibiting oxidizing agents." (PMID 37563630, 2023). "Prior studies have reported that low serum albumin was an independent determinant of poor outcomes after ischemic stroke." (PMID 36794538, 2023). "Serum albumin is commonly used to surrogate nutritional status and is an independent prognostic factor in ischemic stroke." (PMID 36794538, 2023). "Our study proposes a novel and practical nomogram based on early infarct signs, NIHSS scores, uric acid, and albumin-to-globulin ratio that can well predict the probability of HT after intravenous thrombolysis in patients with ischemic stroke." (PMID 36158944, 2022). "In ischemic stroke, serum albumin, a multifunctional protein, exhibits neuroprotective properties, such as preventing erythrocyte aggregation, and posing as a major antioxidant." (PMID 35405949, 2022). "A previous study has demonstrated that low serum albumin is an independent predictor of HT in ischemic stroke patients with intravenous thrombolysis." (PMID 36276820, 2022). "Admission albumin-corrected serum calcium in ischemic stroke patients was positively correlated with 30-day mortality, and the relationship between them was almost linear." (PMID 35785360, 2022). "First, serum albumin is a multifunctional protein that exerts neuroprotective effects in ischemic strokes, such as resisting antioxidants and reducing erythrocyte pressure levels." (PMID 36562034, 2022). "This study proposes a novel and practical nomogram based on early infarct signs, NIHSS scores, uric acid, and albumin-to-globulin ratio that can well predict the probability of HT after intravenous thrombolysis in patients with ischemic stroke." (PMID 36158944, 2022). "In animal models of ischemic stroke, a high concentration of albumin was found to have a significant neuroprotective effect on focal cerebral ischemia." (PMID 35544482, 2022). "Serum-albumin extravasation into brain parenchyma was ~5-fold higher in mice with ischemic stroke than in sham-operated mice (p < 0.05, n = 5–6), suggesting that tMCAO/reperfusion induced disruption of BBB integrity in ischemic brains." (PMID 31911626, 2020). "Patients with ICH had higher serum bilirubin and serum lactate at 24 hours while lesser serum albumin than those with confirmed ischaemic strokes." (PMID 32449052, 2020). "Our results revealed that the serum albumin at admission is an independent predictive factor of the functional outcome in ischemic stroke patients by linear regression statistical analysis which is done to test for significant predictors of outcome." (PMID 30046235, 2018). "Previous studies have highlighted the favorable relationship of serum albumin levels on the outcome of patients experiencing ischemic stroke (IS)." (PMID 26757706, 2016).
ischemic stroke (continued). "Our previous publication using high-resolution LC-MS/MS to profile protein and peptide expression patterns in plasma showed that albumin was relatively increased in donor samples from PFO-related than other types of ischemic strokes." (PMID 25678897, 2015). "Serum albumin is also an accepted negative acute-phase protein, and earlier studies have shown that low serum albumin levels in ischemic stroke patients are associated with increased mortality and prolonged hospitalization." (PMID 40389774, 2025). "In our analysis, although a lower albumin level was associated with an increased bleeding risk, there was no corresponding reduction in the risk of ischaemic stroke or systemic embolism." (PMID 40273298, 2025). "Given the characteristics above, we hypothesized that providing albumin after an ischemic stroke could improve long-term results." (PMID 38846203, 2024). "No studies have investigated the association between albumin levels and the risk of early cardiovascular complications in patients with ischemic stroke." (PMID 38323429, 2024). "The initial cohorts consisted of 503 840 patients with ischemic stroke, of whom 320 111 with normal albumin levels ≥3.5 g/dL (mean age, 70.9±14.7 years; 48.9% females) and 183 729 with reduced albumin levels ≤3.4 g/dL (mean age, 72.9±14.3 years; 50.3% females)." (PMID 38323429, 2024). "The correlation between blood albumin levels and prognosis may be attributed to the acknowledged impact of these comorbidities on ischemic stroke outcomes." (PMID 38846203, 2024). "In experimental ischemic stroke models, exogenous human serum ALB is neuroprotective by promoting amelioration of brain swelling, preventing postischemic thrombosis, antioxidation, hemodilution, and improving microvascular hemoperfusion to increase the perfusion volume of the ischemic tissue." (PMID 37153679, 2023). "In conclusion, serum transferrin, albumin, and prealbumin levels in patients with ischemic stroke may correlate with dysphonia severity as assessed using DSI and MPT." (PMID 36771359, 2023). "Serum transferrin, albumin, and prealbumin levels in patients who have suffered an ischemic stroke may correlate with dysphonia severity as assessed using DSI and MPT." (PMID 36771359, 2023). "Our aim was to retrospectively investigate whether low eGFR and albuminuria, as indicated by the urine albumin-creatinine ratio (UACR), are independently or jointly associated with worse cognitive performance in patients with ischemic stroke." (PMID 38096197, 2023). "The fibrinogen-to-albumin ratio (FAR), as a simple and inexpensive method for assessing inflammation, is attracting attention as a new prognostic marker for ischemic stroke and may be able to predict the long-term risk of cardiovascular events." (PMID 37305748, 2023). "Serum albumin levels can predict the prognosis of ischemic stroke." (PMID 33510706, 2020). "Serum albumin levels has been shown to predict outcome in ischemic stroke patients." (PMID 28798356, 2017). "This further demonstrates the neuroprotective effect of albumin in ischemic stroke." (PMID 28798356, 2017). "These experimental evidences are in agreement with our finding observed in humans showing that low serum levels of albumin are associated with elevated NIHSS score at 7 days, suggesting that high albumin is neuroprotective in ischemic stroke for both lesion gravity and clinical outcome." (PMID 23110752, 2012). "Although the mechanisms through such composite albumin-based malnutritional markers influence clinical outcomes in ischemic stroke patients following reperfusion therapy remain incompletely elucidated, several potential pathophysiological pathways have been hypothesized." (PMID 40832639, 2025). "Consequently, numerous studies have explored albumin as a neuroprotectant in ischemic stroke." (PMID 41468394, 2025).
ischemic stroke (continued). "However, there are no studies on the association between serum transferrin, albumin, and prealbumin and dysphonia severity in patients who have suffered an ischemic stroke." (PMID 36771359, 2023). "Therefore, we may need to design trials with appropriate doses of albumin and longer follow‐up to evaluate the effects of albumin in patients with ischemic stroke." (PMID 36794538, 2023). "A recent study shows that albumin protein-formed nanoparticles loaded with doxorubicin could induce neutrophil apoptosis, thus inhibiting neutrophil infiltration to prevent brain damage in a mouse ischemic stroke model." (PMID 33066616, 2020). "ALB can effectively reduce infarct volume and cerebral edema while decreasing BBB permeability in ischemic stroke." (PMID 38376013, 2024). "According to the Chinese guideline, all patients with ischemic stroke should receive NCCT, blood glucose, and laboratory tests including uric acid and albumin to globulin ratio before intravenous thrombolysis." (PMID 36158944, 2022). "There are differences in serum albumin level and ALB level between different patients with ischemic stroke." (PMID 33505489, 2021). "Compared to the first tertile, there were more patients with favorable outcomes, more patients under 60 years old, more females, higher RBC levels, higher levels of hemoglobin, albumin, HCT, MCH, MCHC, HDL-C, and protein, and more patients with ischemic stroke type of LAA in the third tertile." (PMID 40248032, 2025). "There was evidence that inflammatory and nutritional indicators calculated based on routine blood parameters at admission, such as neutrophils, lymphocytes, serum albumin and total cholesterol, can provide valuable prognostic information for various diseases, including ICH and ischemic stroke." (PMID 37464311, 2023). "In the case of ischemic stroke, HA did not beneficially affect long-term neurological function, and concerns have been raised regarding cardiac complications after albumin infusion." (PMID 37762860, 2023). "Ischemic stroke (IS) is a common neurological disease in the elderly, but the relationship between neutrophil/albumin ratio (NAR) and leukocyte count/albumin ratio (LAR) and the severity of neurological function injury and early neurological deterioration (END) occurrence remain elusive in acute IS." (PMID 36969491, 2023). "Moreover, ligustrazine, safflower yellow, statins, albumin, colchicine, MLC601, salvianolic acids, and DL-3-n-butylphthalide showed serious adverse events, intracranial hemorrhage, or mortality in ischemic stroke patients." (PMID 35935837, 2022). "Without β-blockers, lower serum albumin and abnormal thyroid function increase readmission and death risks in elderly HF patients who have had an ischemic stroke at 3 months and 1 year after discharge." (PMID 36233790, 2022). "Clinical trials for ischemic stroke demonstrated high dose albumin therapy but have no benefit, and it even increased myocardial stress." (PMID 36384553, 2022). "Since then, hyper-oncotic albumin has not been recommended for the treatment of patients with ischemic stroke." (PMID 33013661, 2020). "For example, the Albumin in Acute Stroke study required patients to have an ischemic stroke and baseline NIHSS score of 6 or higher and the Desmoteplase in Acute Ischemic Stroke3 study required patients to have an ischemic stroke and NIHSS score of 4–24." (PMID 31914991, 2020). "Meanwhile, we did not carried out the relationship between albumin levels and function outcomes in ischemic stroke subtypes." (PMID 28798356, 2017). "However, the role of blood urea nitrogen(BUN)to serum albumin ratio (BAR) in predicting in-hospital mortality of T2DM patients with ischemic stroke has not been fully explored." (PMID 40929100, 2025). "However, numerous clinical trials and meta-analyses have not confirmed that early albumin therapy improves neurological function or reduces 90-day and 180-day mortality rates in ischemic stroke patients." (PMID 41468394, 2025).